FAM47C (family with sequence similarity 47 member C)
Tractability: No criterion of Open Targets' tractability assessment is met for any kind of drug.
Gene: Protein-coding gene on chromosome X (37,008,366 to 37,011,664, forward strand). Ensembl gene ENSG00000198173.
Homologues: Orthologues: chimpanzee FAM47C (48% identical), Drosophila melanogaster Frl (11% identical), Caenorhabditis elegans frl-1 (10% identical), Drosophila melanogaster dia (9% identical), zebrafish fmn2b (9% identical), Caenorhabditis elegans daam-1 (9% identical), Drosophila melanogaster capu (8% identical), Caenorhabditis elegans exc-6 (8% identical), Drosophila melanogaster form3 (8% identical), Caenorhabditis elegans fhod-1 (7% identical), Caenorhabditis elegans cyk-1 (6% identical), zebrafish fhdc2 (6% identical), and 1 more. Paralogues in human: FAM47A (51% identical), FAM47B (47% identical), FMNL1 (12% identical), FMNL2 (12% identical), DIAPH1 (12% identical), FMNL3 (11% identical), DIAPH2 (11% identical), INF2 (11% identical), DIAPH3 (10% identical), DAAM2 (10% identical), FMN2 (10% identical), DAAM1 (10% identical), and 6 more.
Diseases named in the same sentence as FAM47C in open-access papers:
FAM47C is named in the same sentence as 4 diseases in open-access papers, as found by Europe PMC text mining. Sharing a sentence is not in itself a finding about the gene and the disease. The quoted sentences say what the papers report.
male fertility (1 paper, 2025). A fertility quality of inhering in a male by virtue of the bearer's disposition to initiate, sustain, or support reproduction. "Studies have shown that FAM47C is associated with male fertility." (PMID 39858210, 2025).
FAM47C also shares sentences with these, for which no sentence is quoted: cancer (1 paper); Infertility (1); tumor (1).